RTL9 (retrotransposon Gag like 9)
Synonyms: KIAA1318; RGAG1; Mart9; Mar9; SIRH10
Tractability: No criterion of Open Targets' tractability assessment is met for any kind of drug.
Gene: Protein-coding gene on chromosome X (110,358,848 to 110,456,334, forward strand). Ensembl gene ENSG00000243978.
Homologues: Orthologues: chimpanzee RTL9 (98% identical), macaque RTL9 (93% identical), dog RTL9 (71% identical), pig RTL9 (71% identical), rabbit RTL9 (70% identical), rat Rtl9 (68% identical), mouse Rtl9 (68% identical), zebrafish vap (8% identical), Caenorhabditis elegans dec-7 (8% identical), Drosophila melanogaster mesh (7% identical), Caenorhabditis elegans F54D1.6 (7% identical), Caenorhabditis elegans R09E10.5 (7% identical). Paralogues in human: MUC4 (9% identical), SUSD2 (9% identical).
Diseases named in the same sentence as RTL9 in open-access papers:
RTL9 is named in the same sentence as 11 diseases in open-access papers, as found by Europe PMC text mining. Sharing a sentence is not in itself a finding about the gene and the disease. The quoted sentences say what the papers report.
fungal infection (1 paper, 2023). "As defects in these cells reduce host resistance to fungal infection, RTL9 is a novel target for antifungal therapy as well as neurodegenerative diseases as a newly identified member of innate antifungal immunity in eutherians." (PMID 37834332, 2023).
RTL9 also shares sentences with these, for which no sentence is quoted: bacterial infection (1 paper); dyslipidemia (1); embryonal carcinoma (1); neurodegenerative disease (1); seminoma (1); soft tissue sarcoma (1); soft tissue tumors (1); tumor (1); uterine sarcoma (1); yolk-sac tumour (1).